OR2L8 (olfactory receptor family 2 subfamily L member 8)
Description:
Odorant receptor.
Tractability: Antibody: UniProt places it where antibodies can reach, with medium confidence; UniProt predicts a signal peptide or a membrane-spanning region; its Gene Ontology location is reachable by antibodies, with medium confidence.
Gene: Protein-coding gene on chromosome 1 (247,948,858 to 247,949,796, forward strand). Ensembl gene ENSG00000279263.
Subcellular location: Cell membrane
Pathways (Reactome):
Sensory Perception: Expression and translocation of olfactory receptors
Gene Ontology:
Molecular function: olfactory receptor activity; G protein-coupled receptor activity
Biological process: detection of chemical stimulus involved in sensory perception of smell; G protein-coupled receptor signaling pathway
Cellular component: plasma membrane; membrane
Genetic constraint (gnomAD): Loss-of-function variants: 0 observed, 0.2 expected, observed/expected ratio (o/e) 0, 90% interval 0 to 1.88. That is too few expected variants to judge how well the gene tolerates losing a copy. Missense variants: 324 observed, 370.43 expected, observed/expected ratio (o/e) 0.87, 90% interval 0.8 to 0.96. Synonymous variants: 123 observed, 134.37 expected, observed/expected ratio (o/e) 0.92, 90% interval 0.79 to 1.06.
Homologues: Orthologues: chimpanzee OR2L8 (97% identical), dog OR2L3 (82% identical), dog OR2L3B (82% identical), dog OR2L5 (82% identical), dog OR2L5C (82% identical), dog OR2L17 (79% identical), mouse Or2l5 (79% identical), rat Or2l5 (79% identical). Paralogues in human: OR2L3 (96% identical), OR2L5 (88% identical), OR2L2 (86% identical), OR2L13 (70% identical), OR2AK2 (57% identical), OR2AJ1 (54% identical), OR2M2 (53% identical), OR2M5 (53% identical), OR2M3 (53% identical), OR2V2 (52% identical), OR2T1 (51% identical), OR2M4 (51% identical), and 80 more.
Diseases named in the same sentence as OR2L8 in open-access papers:
OR2L8 is named in the same sentence as 2 diseases in open-access papers, as found by Europe PMC text mining. Sharing a sentence is not in itself a finding about the gene and the disease. The quoted sentences say what the papers report.
Obesity (1 paper, 2023). Accumulation of substantial excess body fat. "OR4D1, and OR52K1 gene scores were positively correlated with obesity, and OR2L8 and CALML3 gene scores were negatively correlated with obesity." (PMID 37664850, 2023).
OR2L8 also shares sentences with these, for which no sentence is quoted: cancer (1 paper).